LDHA (lactate dehydrogenase A)
Diseases named in the same sentence as LDHA in open-access papers (continued):
Sharing a sentence is not in itself a finding about the gene and the disease.
tumor (continued). "This is the reason why many cancer cells may show an increased expression of antioxidant proteins such as LDHA and TKTL1 as indicated by our observation, which contribute to the survival and success of the tumor." (PMID 25048361, 2014). "The lactate dehydrogenase A (LDHA) protein, a target gene of c-Myc and hypoxia-inducible factor (HIF-1) located on the short p arm of chromosome 11 (11p15.4), is considered to be a critical branch point in metabolism of tumor cells." (PMID 24885701, 2014). "Surprisingly, we found an overexpression of the lactate dehydrogenase B enzyme in certain cancers and no significant upregulation of the lactate dehydrogenase A enzyme that has been suggested to have a ubiquitous role in tumor metabolism and growth." (PMID 25243088, 2014). "In the present study, LDHA was predominantly expressed in tumor cells rather than in vascular tissues." (PMID 23456655, 2013). "The correlation between protein and mRNA levels for LDHA and LDHB was less relevant, but related to previous studies on cell metabolism where a mix between aerobic and anaerobic glycolysis was described in normal and tumor cells." (PMID 23516535, 2013). "The expression levels of LDHA and SLC16A1 in LGG and control samples were extracted from TCGA and GTEx expression profile datasets, and the expression differences of LDHA and SLC16A1 in the tumor vs. normal groups were analyzed by R Wilcoxon test according to grading." (PMID 40782248, 2025). "Hypoxic tumor cores exhibit glycolytic dependency mediated by HIF-1α stabilization, targetable through HIF-1α inhibitors (adamantane derivatives, MO-2097, NLG207, NB-5-MT), combined with glycolytic enzyme blockade (HK2 inhibitor PF-04691502, LDHA inhibitor FX-11)." (PMID 40725147, 2025). "Furthermore, succinate delivered via tumor-derived microvesicles triggers succinylation of isocitrate dehydrogenase 2 (IDH2) and histone H3K122, thereby enhancing lactate dehydrogenase A (LDHA) expression and forming a positive feedback loop that promotes glycolysis." (PMID 41459510, 2025). "Thus, the contribution of LDHA and MCT1 (SLC16A1) to tumor progression deserves attention." (PMID 40782248, 2025). "Oxamate, as an LDHA inhibitor, is able to reprogram glucose metabolism in cancer stem cells, reduce histone H3K18 lactate levels, and inhibit lactate production alter the phenotype of tumor-infiltrating car-t cells in animal models, and mitigate immunosuppression of the tumor microenvironment." (PMID 41041328, 2025). "For example, studies could consider a triple therapy design, simultaneously targeting glucose metabolism (LDHA inhibitor), lipid metabolism (FASN inhibitor), and immune checkpoints (anti-PD-1), and remodeling the “hot tumor” microenvironment through metabolic reprogramming." (PMID 40426972, 2025). "To determine the effects of miR-4259 on LDHA protein expression and gemcitabine resistance, we overexpressed miR-4259 in PANC-/GEM cells and found that the LDHA expression (left), LDH activity, lactate production, tumor initiating capacity and gemcitabine resistance were repressed by miR-4259." (PMID 39930542, 2025). "Hypoxia enhances glycolytic flux by upregulating GLUT1/LDHA, and intracellular lactate accumulation triggers p300-induced histone H3K18 lactylation modification, directly regulating arginase-1 (ARG1) expression to suppress CD8+/CD4+ T cell activity and promote tumor immune escape." (PMID 41181157, 2025). "Additionally, alternative strategies have been proposed, including targeting MCT1 to diminish lactate uptake and inhibiting lactate dehydrogenase A (LDHA) to prevent lactate production, aimed at directly reducing lactate levels and activating T-cell-mediated anti-tumor immunity." (PMID 40161377, 2025).
tumor (continued). "In functional assays, RNA interference–mediated knockdown of LDHA or pharmacologic inhibition with the LDHA inhibitor FX11 reduced glycolytic activity, suppressed GBC cell proliferation, invasion and colony formation, promoted apoptosis in vitro, and inhibited tumor growth in vivo." (PMID 41458606, 2025). "However, in tumor cells or under hypoxic stress, the activity of PDH is often suppressed through inhibitory phosphorylation by pyruvate dehydrogenase kinases (PDKs), diverting pyruvate toward lactate dehydrogenase A (LDHA)-mediated conversion into lactate." (PMID 41458606, 2025). "In depth analysis demonstrated that GLUT3 could promote histone modifications by regulating LDHA in GC, suggesting the possible interactions between glycolytic enzymes to facilitate non-metabolic activities in tumour progression." (PMID 41154605, 2025). "The tumor cell line LS174T was used in the xenograft tumor mouse model because a radiosensitizing effect by diclofenac could be demonstrated for this cell line in vitro, and because a LDHA and LDHB gene knockout resulted in an increased radiosensitivity." (PMID 38229111, 2024). "Moreover, RNA sequencing (RNA-seq) using tumor tissues from the Alb-Cre;S225Kfl/fl and S225Kfl/fl groups showed that SIX1 S225K knock-in regulated expression of many genes, including the glycolytic genes LDHA, ENO1, and PKM." (PMID 39617783, 2024). "Therefore, targeting the lactate metabolism and signaling pathways of tumor cells may be an effective strategy for PC treatment, such as targeting NUSAP1 or inhibiting LDHA." (PMID 39010066, 2024). "Additionally, the protein levels of GLUT1, LDHA, HK2 and VEGF in tumor tissues declined with melittin treatment compared with the hypoxia group, and the levels of these proteins were remarkably increased in the hypoxia+melittin+si-LATS2 group compared to that in the hypoxia+melittin group." (PMID 38889502, 2024). "In addition, in a model of HFSC-induced tumorigenesis, we found that deletion of LDHA did not markedly affect tumor production but did show evidence of metabolic compensation by glutaminolysis." (PMID 39303037, 2024). "The high expression of CCR3 and LDHA in tumor tissue is not prominent." (PMID 38511143, 2024). "In addition, tumor cells need to increase their efficiency by increasing glucose transporters, or various key enzymes, such as hexokinase 2 (HK2), pyruvate kinase M2 (PKM2), lactate dehydrogenase A (LDHA), aldolase C (ALDOC), alcohol dehydrogenase gene (ADH6)." (PMID 39438468, 2024). "This suggests that, in the absence of immunity, ALDH1A1 influences tumor growth by regulating LDHA." (PMID 39107297, 2024). "This study showed that CTTPPPD could significantly reduce LDHA expression, suggesting that CTTPPPD may inhibit the glycolytic pathway of tumor cells and reduce energy production and, thereby, inhibit the growth of tumor cells." (PMID 39275122, 2024). "ICB therapy may be particularly effective when rewiring the metabolic phenotype of effector T cells or targeting cancer metabolism to render tumor cells low-glycolytic activity or low LDHA-expression, thus enabling activated CD8+ T cells to manifest within the tumor microenvironment." (PMID 38216787, 2024). "In addition, the tumor infiltration of CD8+ T cells and the expression of GraB and IFN-γ were increased by FX11, and similar trends in the expression of GraB and IFN-γ were also observed in tumors with LDHA silencing." (PMID 37733442, 2023). "We also provided evidence that metabolic interventions by depleting LDHA and GLS (a key enzyme of glutaminolysis), which are two metabolic targets under investigations in clinical trials for cancer therapy, abrogated the anti-tumor response of TAMs induced by agonistic anti-CD40 antibody." (PMID 37740232, 2023).
tumor (continued). "Given the significance of LDHA expression in fibrotic tumor formation observed in the orthotopic mouse model, we next evaluated the CAF volume in 190 resected PDAC tumor tissues by αSMA staining to investigate the relationship between CAFs and LDHA expression in human PDAC tumors." (PMID 37733442, 2023). "After the knockout of both LDHA and LDHB, aerobic glycolysis was disrupted, tumor growth was delayed but not abolished, and glucose metabolism was transformed to oxidative phosphorylation, indicating that tumor metabolism is a complex and flexible process and the Warburg effect is not irreplaceable." (PMID 37576895, 2023). "The authors also uncovered a correlation between the [1-13C]lactate signal with both LDHA (epithelial) and MCT-4 (ratio of epithelium-to-stroma), highlighting the potential of HP 13C MRSI to stratify patients based on metabolic differences in the epithelial and stromal tumor compartments." (PMID 37444583, 2023). "Silencing of LDHA reduces tumor mass irrespective of cancer xenografts." (PMID 37762231, 2023). "It was reported that tyrosine residues of LDHA were subject to phosphorylation by various kinases in cancer cells and provided metabolic advantages to tumor growth, but we did not notice significant changes of these signal pathways in the (phospho)proteomic study." (PMID 36732657, 2023). "Phenformin treatment improved the survival of control tumor‐bearing mice but not of LDHA/B KO tumor‐bearing mice, but cranial irradiation massively increased global mouse survival, with higher efficiency for mice bearing double LDHA/B KO tumors." (PMID 36278433, 2022). "Inhibition of LDHA has no significant toxic effects on normal tissues; therefore, LDHA may serve as a promising target for tumor therapy." (PMID 35252177, 2022). "The HIF-1α could induce the activation of lactate dehydrogenase A (LDHA) and pyruvate dehydrogenase kinase 1 (PDK1) to catalyze the conversion of pyruvate to lactate, accordingly promote glycolysis to produce ATP in the anoxic tumor microenvironment." (PMID 35662730, 2022). "In the present study, higher expression of LDHA indicated worse OS, which suggests that higher LDHA in LUAD might help enhance fat synthesis by promoting acetyl-CoA generation in glycolysis, thus providing more energy for tumor progression." (PMID 35910199, 2022). "HIF-1α, in collaboration with c-Myc, promotes glucose uptake by cells and accelerates tumor cell aerobic glycolysis by increasing the expression of GLUTs (primarily GLUT1 and GLUT3) or additional glycolytic enzymes that rely on HIF-1α (such as LDHA, MCT4, and GAPDH)." (PMID 36276846, 2022). "Higher protein levels of LDHA were observed in the tumor samples compared to the non-tumor samples." (PMID 35205159, 2022). "The tumor center was characterized by a higher abundance of transferrin (TF), endoplasmic reticulum oxidoreductase 1 (ERO1)-like protein (ERO1A), EH domain-containing protein 1 (EHD1), keratin 5 (KRT5), serpin H1 protein (SERPINH1), and lactate dehydrogenase A (LDHA)." (PMID 35512017, 2022). "High LDHA levels in serum can be regarded as a negative prognostic biomarker in malignancies, indicating that a large amount of lactate is secreted from tumor cells into the circulatory system." (PMID 35646923, 2022). "Interestingly, LDHA was the highest fold change in GBM compared to LGG indicating that the conversion of pyruvate to lactate and Warburg related properties were exacerbated during the tumor shift." (PMID 35004842, 2021). "Moreover, the results of this study showed that after treatment with andrographolide, the expression levels of the glycolysis-related proteins HK2, PKM2, PFKM, and LDHA in 8505C and CAL62 thyroid cells decreased, further proving that andrographolide can inhibit glycolysis in ATC tumor cells." (PMID 34335811, 2021).
tumor (continued). "It was previously shown that HIF-2α protein was gradually accumulated in tumor cells and contributed to the prolonged activation of hypoxia-related genes, in which HIF-2α regulated a glycolytic flux by targeting several glycolysis-related genes such as SLC2A1 and LDHA." (PMID 35096814, 2021). "In contrast, basal-like tumours generally exhibit classical Warburg-like phenotypes with high levels of glucose transporter-1 (GLUT1), monocarboxylate transporter 4 (MCT4), and lactate dehydrogenase A (LDHA), allowing high rates of glucose uptake and lactate secretion." (PMID 34572926, 2021). "Importantly, this suggested that BSJPF could inhibit tumor proliferation by enhancing GLUT1- and LDHA-related glycolysis." (PMID 34002799, 2021). "C-Myc can drive glycolysis; upregulate lactate dehydrogenase A (LDHA), hexokinase 2 (HK2), and pyruvate kinase M2 (PKM2); improve the transcription rate of glucose transporter (GLUT); regulate the transcription of monocarboxylate transporters (MCT); and promote tumor growth." (PMID 34434922, 2021). "In addition to the absence of the enzymes LDHA and LDHB (LDH−/−), the LDH activity was significantly reduced in both LDH−/− tumor cell lines, although the expression of the lactate transporter MCT1 remained unaffected by the CRISPR/Cas9-induced LDHA/B double knockout." (PMID 34359663, 2021). "However, the molecular mechanisms of how LDHA contributes to tumor progression and tumor metastasis in PTC have not yet been investigated." (PMID 33795650, 2021). "Tumor volume in MCF7-injected mice was negligible at day 15, but a continuous growth of tumor volume in both the MCF7-POU1F1 and the MCF7-POU1F1-shLDHA groups was observed during the study, being significatively higher at 9, 12, and 15 days in MCF7-POU1F1 mice comparing to LDHA knocked-down mice." (PMID 33714987, 2021). "Therefore, reducing the level of LDHA selectively in tumor cells without affecting normal cell function remains a major challenge." (PMID 32859246, 2020). "Lactate dehydrogenase A (LDHA) and phosphofructokinase P (PFKP) were found to be significantly correlated with progression-free survival (PFS) and OS in patients with CC, and the expression level of LDHA in recurrent tumours was significantly higher than that in nonrecurrent tumours." (PMID 33228592, 2020). "In addition, increased LDHA and decreased LDHB expressions facilitate tumor formation and progression through remodeling of the tumor microenvironment, increasing proliferation, and inducing epithelial-to-mesenchymal transition, cell migration and invasion, and angiogenesis." (PMID 31932876, 2020). "In line with the result of LDHA expression, a gradual rise of Lac/Cr level was observed in BEV-treated tumors, which was more prominent than tumors in control at day 14, indicative of the activation of tumor glycolysis and the deteriorate of acidic microenvironment after BEV treatment." (PMID 32641990, 2020). "Mechanically, the tumor-suppressive effects of CD36 were mediated through promoting the proteasome-dependent ubiquitination of GPC4, and the degraded GPC4 failed to activate β-catenin/c-myc signaling cascades and downstream glycolytic target genes GLUT1, HK2, PKM2 and LDHA." (PMID 31484922, 2019). "Metabolic adaptation to hypoxia in tumours is primarily mediated by HIFs and includes the diversion of glucose-derived carbons from the TCA cycle and the conversion of pyruvate to lactate, and by upregulation of the enzymes pyruvate dehydrogenase kinase 1 (PDK1) and LDHA." (PMID 30886710, 2019). "Interestingly the induction of LDHA was not only seen in tumor cells but also in the non-neoplastic host compartment, an observation that was possible because of the species specific SRM workflow established here." (PMID 26243272, 2016).
tumor (continued). "Similarly, 55 (76.4%) patients with positive LDHA tumour expression had a median survival of 10.9 months compared with 34.5 months of the 17 (23.6%) patients with weak (negative) LDHA tumour expression (p = 0.029, log-rank test)." (PMID 26989901, 2016). "To determine if MYC family proteins could cooperate with MCPyV IMR90 cells, we treated cells stably expressing ST, GFP, or p53DD + hTERT (PH) and MCPyV tumor-derived early-region (PHE) with inducible expression of MYC, MYCN or MYCL with dox for 48 hours and immunoblotted for HK2, MCT1 and LDHA." (PMID 27880818, 2016). "Given that PKM2 and LDHA are involved in several cell proliferation signaling pathways, we also investigated whether the expression of these glycolytic enzymes correlated with the number of CD8+TILs and markers of tumour proliferation (Ki-67)." (PMID 26989901, 2016). "Furthermore, knockdown of LDHA has been shown to increase PARP expression, decrease XIAP, Bcl‐2 and Bcl‐XL expression, and attenuate the tumorigenicity of the pancreatic cell line BXPC‐3, reducing the tumor size and weight in vivo xenograft models." (PMID 26269128, 2016). "However, targeting LDHA was mildly effective in tumor tissues lacking CD8+ T lymphocytes." (PMID 40630951, 2025). "Understanding the interplay among CCDC80, LDHA and LDHB could provide insights into the metabolic reprogramming of cancer cells and identify novel targets for therapeutic intervention aimed at restoring normal metabolic processes and enhancing anti-tumor immunity." (PMID 39308689, 2024). "Importantly, although less significant than its effect on G6PD, p52-ZER6 might also affect the expression of other glucose metabolism-related genes, such as FH, PKM2, TIGAR, LDHA, GLUT1, and HK2, thereby contributing to tumor metabolic reprogramming through multiple pathways." (PMID 36977688, 2023). "Moreover, our study did not evaluate the expression level of LDHA in tumor samples." (PMID 33777804, 2021). "However, no suitable LDHA inhibitor has been found for tumor therapy." (PMID 35127693, 2021). "Similar to the results obtained with LDH inhibitors, a LDHA/B double knockout reduced the cytosolic Hsp90, Hsp70 and Hsp27 levels in B16F10 and LS174T cells, although the Hsp27 levels could not be detected in B16F10 cells due to a very low Hsp27 expression in murine tumor cells." (PMID 34359663, 2021). "Therefore, we analyzed the correlation of biomarkers with σ and ε in some characteristics of tumor cells, including proliferation (KI67, cyclinD1), migration, acidic microenvironment (pH, NHE1), hypoxia microenvironment (HIF-1α), and abnormal energy metabolism (LDHA)." (PMID 34253828, 2021). "However, LDHA expression in malignant tumor tissues does not correlate consistently with serum LDH levels, which may indicate that these are independent prognostic factors in cancer." (PMID 32257942, 2020). "Therefore, a significant difference in LDHA and LDHB expression levels with a predominance of LDHA expression i.e., in MDA−MB-231 adenocarcinoma cells, and LDHB in adenocarcinoma MCF-7 cells, can be observed in cells from the same spontaneous tumors or tumor cell lines." (PMID 31035592, 2019). "The re-expression of TPX2WT, but not TPX2K249R, facilitated the in vivo tumour growth of HepG2 xenografts with endogenous TPX2 knockdown, which was abolished by treatment with both LDHA inhibitor, GSK2837808A, and AURKA inhibitor, alisertib." (PMID 40107714, 2025). "We hypothesize that in the double-mutant tumors deleted for LDHA and GLS, HFSCs failed to up-regulate alternative pathways to substitute for the loss of glutaminolysis and lactate utilization as compensatory mechanisms and, as a result, failed to fuel the TCA cycle leading to tumor growth." (PMID 39303037, 2024). "Intriguingly, this modification does not affect LDHA ubiquitination but diminishes the binding of ubiquitinated LDHA with SQSTM1, thereby reducing its lysosomal degradation and promoting tumor invasion and metastasis." (PMID 39010066, 2024).